IQGAP1 (IQ motif containing GTPase activating protein 1)
Diseases named in the same sentence as IQGAP1 in open-access papers (continued):
Sharing a sentence is not in itself a finding about the gene and the disease.
idiopathic pulmonary fibrosis (2 papers, 2024 to 2025). Idiopathic pulmonary fibrosis (IPF) is a nonneoplastic pulmonary disease that is characterized by the formation of scar tissue within the lungs in the absence of any known cause. "We previously reported that lung fibroblasts isolated from patients with scleroderma-associated pulmonary fibrosis are characterized by higher expression of IQGAP1 compared to control lung fibroblasts." (PMID 38791282, 2024). "In idiopathic pulmonary fibrosis, however, IQGAP1 expression is paradoxically diminished in lung fibroblasts and myofibroblasts." (PMID 40149956, 2025). "Pulmonary fibrosis was induced in IQGAP1 knockout (KO) and wild-type (WT) mice by a single-intratracheal instillation of bleomycin." (PMID 38791282, 2024). "To evaluate the effect of IQGAP1 on collagen accumulation in a bleomycin-induced pulmonary fibrosis mouse model, we quantified total soluble collagen content in the lung tissue using the Sircol collagen assay." (PMID 38791282, 2024). "To understand the effect of IQGAP1 in the regulation of actin filament formation in lung fibrosis, we compared differences in the actin polymerization rate between the saline-treated mice (∆Saline) and bleomycin-treated mice (∆Bleo)." (PMID 38791282, 2024). "In conclusion, our results identify IQGAP1 as a scaffolding protein contributing to bleomycin-induced pulmonary fibrosis and strongly suggest that IQGAP1 participates in SSc-ILD pathophysiology by increasing contractile forces and lung stiffness." (PMID 38791282, 2024). "Our current study demonstrates significantly higher expression of IQGAP1 in lung tissue from mice with bleomycin-induced pulmonary fibrosis." (PMID 38791282, 2024). "Indeed, IQGAP1 knockout mice develop exacerbated pulmonary fibrosis in some studies, but others have reported the opposite trend." (PMID 40149956, 2025). "Similar effects on actin polymerization were observed in mice with bleomycin-induced pulmonary fibrosis; the actin polymerization rate decreased by 23% during growth phase and by 29% during the steady-state phase in IQGAP1-KO mice compared to WT mice on day 21 after bleomycin administration." (PMID 38791282, 2024). "We conclude that IQGAP1 plays an important role in the development of lung fibrosis induced by bleomycin, and the absence of IQGAP1 reduces the contractile activity of lung fibroblast and bleomycin-induced pulmonary fibrosis." (PMID 38791282, 2024). "Bleomycin-induced pulmonary fibrosis was less severe in IQGAP1-KO mice." (PMID 38791282, 2024). "Moreover, findings on IQGAP1 expression in pulmonary fibrosis are somewhat contradictory." (PMID 38791282, 2024). "Thus, IQGAP1 may be a novel target for the development of much-needed anti-fibrotic therapy for SSc-ILD as well as for other diseases characterized by lung fibrosis." (PMID 38791282, 2024). "Thus, IQGAP1 may be a potential target for novel anti-fibrotic therapies for lung fibrosis." (PMID 38791282, 2024). "Lung fibroblasts isolated from bleomycin-administrated WT mice exhibited higher expression of SMA and more profound contractile activity, suggesting that IQGAP1 is an important regulator of SMA expression and contractile forces in bleomycin-induced pulmonary fibrosis." (PMID 38791282, 2024). "However, direct proof of IQGAP1′s involvement in pulmonary fibrosis in vivo has been lacking." (PMID 38791282, 2024).
leukemia (2 papers, 2020 to 2024). A malignant (clonal) hematologic disorder, involving hematopoietic stem cells and characterized by the presence of primitive or atypical myeloid or lymphoid cells in the bone marrow and the blood. "Compared to naive and scrambled shRNA transfected K652, MV411 and THP1 leukemia cells, transfection with IQGAP1 shRNAs caused robust suppression of proliferation." (PMID 38834690, 2024). "In TRPM2-depleted leukemia cells, expression of IQGAP1 is decreased, contributing to reduced Nrf2 stability." (PMID 32312983, 2020). "shRNA knockdown of IQGAP1 blocked proliferation and clonogenicity of human leukemia cell-lines." (PMID 38834690, 2024). "shRNA knockdown of IQGAP1 blocked proliferation and colony formation in human leukemia cell-lines." (PMID 38834690, 2024). "Similarly, shRNA knockdown of IQGAP1 in K652, MV411 and THP1 leukemia cells resulted in the significant reduction in the number of colonies formed compared to those generated from cells transfected with scrambled shRNA or untransfected controls." (PMID 38834690, 2024).
liver fibrosis (2 papers, 2022). "Finally, recently it has been shown that miR-124, a 3′-UTR of IQGAP1, might be associated with the development of inflammation in liver fibrosis." (PMID 35563891, 2022). "It implies that IQGAP1 might have a potential role in the modulation of liver fibrosis." (PMID 35785216, 2022). "Likewise, in a recent study, mRNA and protein levels of IQGAP1 were shown to be significantly elevated in CCl4-induced liver fibrosis mice and TNF-α-treated hepatic stellate cell (HSC) line, LX-2 cells, which might be related to the development and advancement of liver fibrosis." (PMID 35785216, 2022). "IQGAP1 expression was found to be remarkably elevated in non-parenchymal cells and myofibroblasts during murine liver fibrosis." (PMID 35785216, 2022).
lymph node metastasis (2 papers, 2014 to 2021). "The coexpression of IQGAP1 and Dvl in the cytoplasm and nucleus was associated with lymph node metastasis and poor prognosis in NSCLC." (PMID 25436461, 2014). "Recent research suggests that IQGAP1 is a risk factor for lymph node metastasis of lung squamous cell carcinomas." (PMID 25436461, 2014).
metastatic cancer (2 papers, 2019 to 2020). A carcinoma which has spread from the original site of growth to another anatomic site. "The exact roles of IQGAP1 in metastasis merit further study, and IQGAP1 may represent a therapeutic target for metastatic cancer." (PMID 32051509, 2020).
metastatic tumor (2 papers, 2020 to 2022). "Given that IQGAP1 knockdown and knockout both decrease experimental metastasis from circulation, IQGAP1 must at least be relevant in the later stages of the metastatic cascade, including arrest, extravasation, early survival and proliferation into a full metastatic tumor." (PMID 32051509, 2020). "Furthermore, the diversity of roles performed by IQGAP1 could conceivably implicate it in any or all of the steps of the metastatic cascade: invasion from the primary tumor, intravasation, survival in circulation, extravasation, and outgrowth of the metastatic tumor." (PMID 32051509, 2020). "We find that reduction of IQGAP1 expression decreases the formation of both spontaneous and experimental metastases, without limiting primary or metastatic tumor growth." (PMID 32051509, 2020).
multiple sclerosis (2 papers, 2016 to 2025). A progressive autoimmune disorder affecting the central nervous system resulting in demyelination. "Consistent allelic imbalance was observed for rs907091 in IKZF3 and rs11609 in IQGAP1, which are in strong linkage disequilibrium with the multiple sclerosis associated single nucleotide polymorphisms rs12946510 and rs8042861, respectively." (PMID 27080863, 2016). "However, different basal levels of IQGAP1 (often regulated through polymorphisms either in the gene itself or regulatory microRNAs) have been linked to human cognitive performance and multiple sclerosis." (PMID 40862773, 2025). "Furthermore, individuals homozygous for the multiple sclerosis risk allele at IQGAP1 had a significantly higher total expression of IQGAP1 compared to individuals homozygous for the protective allele." (PMID 27080863, 2016). "Our data indicate a possible regulatory role for the multiple sclerosis-associated IKZF3 and IQGAP1 variants." (PMID 27080863, 2016). "Using multiple sclerosis patients and healthy controls heterozygous for rs907091 and rs11609, we showed that the multiple sclerosis risk alleles at IKZF3 and IQGAP1 are expressed at higher levels as compared to the protective allele." (PMID 27080863, 2016). "We suggest that such cis-acting mechanisms may contribute to the multiple sclerosis association of single nucleotide polymorphisms at IKZF3 and IQGAP1." (PMID 27080863, 2016).
nasopharyngeal carcinoma (2 papers, 2021 to 2024). A carcinoma arising from the nasopharyngeal epithelium. "Against this background, we aimed to determine the expression pattern of AKT, IQGAP1 and MMP16, in HPV‐associated cervical and nasopharyngeal cancer tissues." (PMID 39073693, 2024). "Thus, examining the expression patterns of AKT, IQGAP1 and MMP16 mRNA and proteins in HPV‐related cervical and nasopharyngeal cancers will shed more light on HPV‐associated carcinogenesis." (PMID 39073693, 2024). "Current study reports AKT but not IQGAP1 and MMP16 mRNAs differentially expression in cervical and nasopharyngeal cancers, independent of HPV infection status." (PMID 39073693, 2024).
osteoarthritis (2 papers, 2021 to 2024). A noninflammatory degenerative joint disease occurring chiefly in older persons, characterized by degeneration of the articular cartilage, hypertrophy of bone at the margins and changes in the synovial membrane. "Circ‐IQGAP1 promotes IL‐1β‐induced chondrocyte apoptosis, inflammation, and extracellular matrix degradation by miR‐671‐5p/TCF4 axis in osteoarthritis." (PMID 33675175, 2021).
renal fibrosis (2 papers, 2016 to 2026). A final common manifestation of a wide variety of chronic kidney diseases characterized by glomerulosclerosis and tubulointerstitial fibrosis. "For example, upregulation of DEPs VIM, IQGAP1, and moesin is closely related to EMT and renal fibrosis, and GSN, another DEP, is related to renal tubule epithelial cell apoptosis." (PMID 27036204, 2016).
schizophrenia (2 papers, 2024 to 2026). A major psychotic disorder characterized by abnormalities in the perception or expression of reality. "Placentae from ∆9-tetrahydrocannabinol-exposed males and females revealed altered expression of genes previously identified in human transcriptomic datasets of schizophrenia (i.e., Furin, Rccd1, and Atp5mk), with some expression changes being sex-specific (i.e., Eif5, Rps10, Vps33b, and Iqgap1)." (PMID 40827685, 2026).
skin carcinoma (2 papers, 2017 to 2020). "This property of IQGAP1 is at least essential in skin cancer, as targeting IQGAP1-facilitated ERK activation inhibited skin cancer tumorigenesis." (PMID 33266355, 2020).
acute myocardial infarction (1 paper, 2025). Necrosis of the myocardium, as a result of interruption of the blood supply to the area. "Elevated expression levels of RAC1, IQGAP1, MYL6, DBN1, SLC2A1 and SLC2A3 were observed in acute myocardial infarction patients compared to healthy controls, suggesting a strong association with disease progression and indicating their potential as novel therapeutic targets." (PMID 40672380, 2025).
age-related macular degeneration (1 paper, 2023). Age-related loss of vision in the central portion of the retina (macula), secondary to retinal degeneration. "VPS54 is reported to be associated with Retinitis pigmentosa; IQGAP1 is reported to regulate choroidal vascularization in Age-Related Macular Degeneration; NMB is involved in RPE homeostasis regulation; MC5R is reported to regulate lacrimal gland function." (PMID 37359372, 2023). "Moreover, IQGAP1 is reported to regulate retinal neurite growth in chicken retina and to play a key role in the regulation of choroidal endothelial cells in the pathogenesis of Age-related Macular Degeneration." (PMID 37359372, 2023).
Anxiety (1 paper, 2022). Intense feelings of nervousness, tension, or panic often arise in response to interpersonal stresses. "The levels of miR-124 and IQGAP1 are correlated with anxiety and depression symptoms, miR-124 and its target protein IQGAP1 are involved in regulating addiction and cognitive function in patients with morphine dependence." (PMID 35401251, 2022).
astrocytoma (1 paper, 2006). "Iqgap1 has also been found to localize to areas of membrane ruffling and newly formed vesicles in astrocytoma cells." (PMID 16670020, 2006).
autoimmune disease (1 paper, 2025). A disorder resulting from loss of function or tissue destruction of an organ or multiple organs, arising from humoral or cellular immune responses of the individual to their own tissue constituents. "In addition to its role in cancer, IQGAP1 is implicated in immune system modulation, particularly in autoimmune diseases where its regulatory functions may affect the development and progression of inflammation and immune responses." (PMID 41035668, 2025).
bipolar disorder (1 paper, 2023). A disorder of the brain that causes unusual shifts in mood, energy, activity levels and the ability to carry out day-to-day tasks. "PKA and GSK3 are protein kinases whereas IQGAP1 is a GTPase activating protein (GAP) for the small G-proteins, CDC42 and Rac1, both of which play essential roles in neurogenesis and display altered expression in bipolar disorder." (PMID 37730845, 2023).
breast adenocarcinoma (1 paper, 2008). "It has been shown that over-expression of IQGAP1 enhances the capacity of human breast adenocarcinoma MCF-7 cell for transmembrane migration by up-regulating the expression active CDC42 and Rac1." (PMID 19036171, 2008).
Breast Invasive Carcinoma (1 paper, 2021). "We analyzed Breast Invasive Carcinoma, TCGA, Firehose Legacy data and observed a negative correlation between MAPK1_PY187 and IQGAP2, whereas a non-significant but positive correlation was observed between MAPK1_PY187 and IQGAP1." (PMID 33846302, 2021).
breast tumors (1 paper, 2013). "We thus postulate that in breast tumors, LPA1 activation recruits β-arrestins and leads to the activation of Rap1, and signaling via IQGAP1." (PMID 23405264, 2013).
cardiac hypertrophy (1 paper, 2016). "IQGAP1 also acts as a membrane-bound MAPK scaffold to regulate responses associated with cardiac hypertrophy." (PMID 26973524, 2016). "Mechanisms underlying the effects of IQGAP1 in cardiac hypertrophy may be due to a direct interaction with melusin." (PMID 26973524, 2016). "However, upon prolonged pressure overload, IQGAP1 null mice displayed unfavorable cardiac remodeling, contractile dysfunction, impaired cardiac hypertrophy, and increased apoptosis when compared with control mice." (PMID 26973524, 2016).
cerebellar pilocytic astrocytoma (1 paper, 2013). A WHO Grade 1 astrocytoma which arises in the cerebellum. "Hypothalamo-chiasmatic pilocytic astrocytomas and cerebellar pilocytic astrocytomas have a distinctive gene signature and several differential expressed genes (ICAM1, CRK, CD36, and IQGAP1) are targets for available drugs: fluvastatin and/or celecoxib." (PMID 24252689, 2013).
cognitive deficits (1 paper, 2023). "Like SigmaR1, IQGAP1 promotes ROS via Rac1 GTPase, and studies in mouse models have implicated IQGAP1 in memory and cognitive deficits." (PMID 37444574, 2023).
ductal breast carcinomas (1 paper, 2025). "Quantitative analysis of confocal microscopy images revealed distinct patterns of IQGAP1 and PALB2 expression across the two different ductal breast carcinomas after probing with anti-IQGAP1 antibody and anti-C-terminus PALB2 Ab; both cases reported in this study lack the BRCA2-interacting domain." (PMID 40868059, 2025).
E. coli infection (1 paper, 2017). "In the event of E. coli infection, cellular IQGAP1 can be up-regulated by the inoculation of Hcp1, which in turn leads to enhanced MAPK pathway activity and increased cell apoptosis." (PMID 28469997, 2017). "The pathological significance of the MAPK signaling pathway was also demonstrated in this study through the finding that its activation by IQGAP1 was a crucial step in the development of E. coli meningitis." (PMID 28469997, 2017).
Ebola (1 paper, 2017). "Here, the cytoskeleton regulator and scaffold protein IQ-motif-containing GTPase-activating protein 1 (IQGAP1) seems essential for virus virulence and completion of invasion, replication and egress in some viruses including Ebola, Moloney murine leukemia and swine fever." (PMID 29209610, 2017).
Esophageal atresia (1 paper, 2019). A developmental defect resulting in complete obliteration of the lumen of the esophagus such that the esophagus ends in a blind pouch rather than connecting to the stomach. "In a patient with complex congenital cardiac disease including TOF, esophageal atresia with tracheal fistula, bilateral iris coloboma, and clinodactyly of all fifth digits, we identified another stopgain variant p.(Arg766*) in IQGAP1, inherited from his unaffected father." (PMID 30232381, 2019).
fibrosarcoma (1 paper, 2017). A malignant mesenchymal fibroblastic neoplasm affecting the soft tissue and bone. "IQGAP1 could be present in the WRAMP complex in other cell types during retraction, such as HUVEC, C2C12 and HT-1080s human fibrosarcoma cells." (PMID 29240845, 2017).
gastritis (1 paper, 2016). Inflammation of the stomach. "IQGAP1 and E-cadherin were expressed predominantly at the epithelial cell-cell junctions in gastritis." (PMID 27729612, 2016).
glomerular diseases (1 paper, 2012). "Through its connections with foot process cytoskeleton and slit diaphragm proteins, IQGAP1 may control key aspects of podocyte biology and may be important in the pathophysiology of glomerular diseases." (PMID 22662192, 2012). "Then, IQGAP1 may be important in the glomerular barrier integrity and in glomerular disease pathophysiology, through its contribution to key podocyte characteristics (podocyte plasticity, migration and permeability)." (PMID 22662192, 2012).
imbalance (1 paper, 2025). "These pathways are closely associated with immune imbalance, metabolic disorders, and cell adhesion mechanisms in SCI, further underscoring the potential role of IQGAP1 as a key hub gene linking metabolic regulation and immune response." (PMID 41190071, 2025).
Impaired glucose tolerance (1 paper, 2021). An abnormal resistance to glucose, i.e., a reduction in the ability to maintain glucose levels in the blood stream within normal limits following oral or intravenous administration of glucose. "We recently documented that IQGAP1 is necessary for optimal activation of insulin signaling, and mice lacking IQGAP1 have impaired glucose tolerance, which is a fundamental component of type 2 diabetes." (PMID 33191271, 2021).
infertile (1 paper, 2018). "Their results demonstrated 10 over-expressed proteins in the infertile group, including: Ubiquitin-conjugating enzyme E2C binding protein (UBE2C), Cystatin-A (CSTA), Dermcidin (DCD), Ceruloplasmin (CP), Ras GTPase-activating-like protein IQGAP1 (IQGAP1)." (PMID 29881623, 2018).
interstitial lung disease (1 paper, 2024). A diverse group of lung diseases that affect the lung parenchyma. "In this study, we employed IQGAP1 KO mice developed on C57BL/6 and 129J1 backgrounds to comprehend the functional roles of IQGAP1 in interstitial lung disease (ILD)." (PMID 38791282, 2024).
invasive carcinoma (1 paper, 2021). A carcinoma that is not confined to the epithelium, and has spread to the surrounding stroma. "However, the loss of IQGAP1 did not cause a significant reduction in the incidence of invasive carcinoma (Iqgap1+/+ vs. Iqgap1−/−, p = 1; Iqgap1+/+K14E6E7 vs. Iqgap1−/−K14E6E7, p = 0.26, two-sided Fisher’s exact test)." (PMID 34068608, 2021).
invasive ductal carcinoma (1 paper, 2025). "This study provides novel insights into the subcellular distribution and potential interactions between PALB2 and IQGAP1 in human invasive ductal breast carcinoma, with a particular focus on the consequences of truncating PALB2 mutations." (PMID 40868059, 2025). "Future research should further explore how truncated PALB2 alters IQGAP1 function in cytoskeletal remodeling and proliferation dynamics, potentially driving tumor cell plasticity in invasive ductal carcinoma." (PMID 40868059, 2025).